CD36 (CD36 molecule (CD36 blood group))
Diseases named in the same sentence as CD36 in open-access papers (continued):
Sharing a sentence is not in itself a finding about the gene and the disease.
ischemic stroke (19 papers, 2017 to 2025). A stroke disorder caused by obstruction of blood flow to the brain, due to thrombotic (local blood clot formation) or embolic (due to a blood clot or other material traveling from another site) event. "Blood flow could become further impaired as CD36 deficiency reduces microvascular repair and has been linked to ischaemic stroke." (PMID 39503770, 2025). "We used immunohistochemistry to investigate the expression patterns of CD36+ cells following ischemic stroke." (PMID 39451255, 2024). "A study suggested that CD36 in macrophages mediates phagocytosis during the recovery phase and likely plays a reparative role via the resolution of inflammation following ischemic stroke." (PMID 37601043, 2023). "CD36 is involved in tissue repair and resolution of inflammation during the resolution phase of ischemic stroke and is also involved in the clearance of cell debris and phagocytosis." (PMID 37452512, 2023). "Cell surface CD36 expression increases 7 days after ischemic stroke with a concomitant reduction in intracellular CD36 expression." (PMID 37452512, 2023). "Compared to hemorrhagic stroke, CD36 plays a significantly different role in the pathophysiology following an ischemic stroke." (PMID 33498620, 2021). "CD36 mediates innate immunity, participating in the assembly of inflammatory pathways and contributing to reactive oxygen species (ROS) production, and plays a role in macrophage phagocytosis during the resolution phase of ischemic stroke in mice." (PMID 39475881, 2024). "Moreover, it was reported that CD36 in MGs/MΦs contributed to phagocytosis during the resolution phase of ischemic stroke." (PMID 39451255, 2024). "We examined whether CD36+ MGs/MΦs acted as phagocytic scavengers of debris following ischemic stroke." (PMID 39451255, 2024). "In ischemic stroke, CD36 expression is upregulated compared to that in normal brain tissues." (PMID 37452512, 2023). "Notably, it has been shown that PPARγ activation promotes phagocytosis via the mechanism of CD36 upregulation, which is beneficial in both hemorrhagic and ischemic stroke models." (PMID 37601043, 2023). "In a model of ischemic stroke, CD36 KO mice had reduced CCL2/CCR2 expression." (PMID 37452512, 2023). "Moreover, another study revealed that CD36 upregulation in hyperlipidemic subjects considerably aggravated patient outcomes after ischemic stroke." (PMID 33498620, 2021). "In the present study, using a mouse model of ischemic stroke, we found that the L-PGDS–PGD2–DP1 axis was activated and DP1 was expressed in CD36+ MGs/MΦs within ischemic areas." (PMID 39451255, 2024). "For example, the scavenger receptor CD36, which was widely studied in ICH, has also been proved to mediate phagocytosis in ischemic stroke." (PMID 35237132, 2022). "Correspondingly, CNS lesions in experimental models for ischemic stroke and spinal cord injury (SCI), both characterized by high numbers of myelin-containing cells, show increased levels of CD36." (PMID 32718316, 2020). "Thus, it is possible that CD36+ MGs/MΦs regulated by the L-PGDS–PGD2–DP1 axis serve as scavengers in brains with pathological conditions, such as ischemic stroke." (PMID 39451255, 2024). "CD36 plays a negative role in the early phase of ischemic stroke and has a restorative function during the resolution phase." (PMID 37452512, 2023). "However, the role of SSO in inhibiting inflammation either directly or independently of CD36 in ischemic stroke has not been reported." (PMID 29202856, 2017). "Interestingly, most of the top 10 upregulated DEGs, such as Thbs1, CD36, ITGA4, and ADAMTS12, are involved in the function of endothelial cells, as shown in the heatmap, implying a role of NeuroD1 in regulating the gene expression of endothelial cells post ischemic stroke." (PMID 38270116, 2023).
diabetic cardiomyopathy (18 papers, 2017 to 2026). Diabetic cardiomyopathy is a disorder of the heart muscle in people with diabetes. "This is the first in vivo study to demonstrate a causal link between CD36 expression and diabetic cardiomyopathy." (PMID 34940639, 2021). "In our mild model of diabetic cardiomyopathy, we have shown that a greater proportion of the CD36 pool in the heart is S-acylated, and these findings were conserved across diabetic and insulin-resistant species, including rats, mice, pigs, and humans." (PMID 40357580, 2025). "Our previous study demonstrated that AS-IV can reduce the levels of TG and TC, downregulate CD36, and attenuate myocardial dysfunction in diabetic cardiomyopathy rats." (PMID 38572426, 2024). "FA uptake into cardiomyocytes is mainly mediated by CD36, and increased FA uptake in diabetic cardiomyopathy is due to a permanent relocation of CD36 to the sarcolemma." (PMID 37685995, 2023). "Our data are the opposite to the hitherto known concept that CD36 is a detrimental factor for diabetic cardiomyopathy." (PMID 34940639, 2021). "In this study, we explore whether reduced FA use by CD36 ablation suppresses the development of streptozotocin (STZ)-induced diabetic cardiomyopathy." (PMID 34940639, 2021). "It has long been suggested that CD36 is involved in the development of diabetic cardiomyopathy." (PMID 34940639, 2021). "Thus, there has been no direct in vivo evidence showing that expression levels/subcellular localization of CD36 play a role in the development of diabetic cardiomyopathy." (PMID 34940639, 2021). "In this study, we addressed the question of whether limited FA use, as a result of CD36 deletion, is protective against the development of diabetic cardiomyopathy generated by streptozotocin (STZ) treatment." (PMID 34940639, 2021). "Therefore, it is still uncertain to what degree the PPARα–CD36 axis is involved in lipotoxic states in diabetic cardiomyopathy." (PMID 34940639, 2021). "In mice with diabetic cardiomyopathy, FGF21 protects the heart from inflammation and oxidative stress by activating Nrf2 to increase CD36 expression." (PMID 35369322, 2022). "Therefore, we propose that instead of influencing CD36 expression, decreased STIM1 expression in diabetic cardiomyopathy could increase FA uptake by the relocation of CD36 to the sarcolemma through the inactivation of the AKT–mTORC1–v-ATPase signaling pathway (Figure 5➀)." (PMID 37685995, 2023).
diabetic nephropathy (18 papers, 2005 to 2025). "In this research, we discovered that CD36 expression was elevated in the renal tissues of individuals with diabetic nephropathy and had a diagnostic accuracy value (AUC > 0.80)." (PMID 36911691, 2023). "CD36, serving as a receptor for a broad spectrum of ligands, has been found to partially alter cellular metabolic pathways in diabetic kidney disease." (PMID 41438111, 2025). "Consistent with previous findings, SS31, an antioxidant peptide, has been shown to downregulate CD36 expression and improve renal function in diabetic nephropathy, supporting the role of CD36 modulation in renoprotection." (PMID 40496556, 2025). "Soluble CD36 (sCD36), the circulating form of the scavenger receptor CD36, plays a key role in lipid accumulation and inflammation during the progression of diabetic kidney disease (DKD), and has been proposed as a promising non-invasive biomarker." (PMID 40496556, 2025). "This study is one of the first to systematically evaluate changes in soluble CD36 (sCD36) levels in response to GLP-1 receptor agonist (GLP-1RA) therapy based on real-world clinical data from patients with early-stage diabetic kidney disease (DKD)." (PMID 40496556, 2025). "CD36 plays a critical role in the process of inflammation and exerts a proinflammatory effect in many cases, including chronic diseases such as diabetic nephropathy, lupus nephritis, and acute illnesses like acute lung injury." (PMID 39524404, 2024). "The relationship between CD36 and various renal diseases, such as chronic kidney disease, diabetic nephropathy and lupus nephritis, has been reported in the literature." (PMID 39114498, 2024). "Patients with chronic kidney disease (CKD), especially those with diabetic kidney disease, exhibit significant expression of CD36." (PMID 38572426, 2024). "CD36 expression has been found to be upregulated in patients with chronic kidney disease, particularly diabetic nephropathy." (PMID 37622127, 2023). "CD36 promotes the podocyte injury in many kidney diseases including primary nephrotic syndrome, obesity-related glomerulopathy, and diabetic nephropathy." (PMID 35999224, 2022). "Much of the available research of CD36 focuses on obesity-related glomerulopathy, diabetic nephropathy." (PMID 35999224, 2022). "Soluble CD36 is a biomarker of T2D and diabetic nephropathy and coordinates activation of the NLRP3 inflammasome, leading to proinflammatory cytokine release and reduced insulin secretion." (PMID 27864352, 2017). "Thus, the present study identifies a new CD36-dependent molecular signaling pathway that mediates tubular epithelial apoptosis, and may underlie TED and IF, hallmarks of disease progression, specifically in human diabetic nephropathy." (PMID 15737001, 2005).
bladder cancer (17 papers, 2020 to 2026). "In bladder cancer, CD36 is implicated in tumoral cells proliferation, survival, and adaptation to metabolic stress, epithelial-mesenchymal transition (EMT) and influences the tumor microenvironment, through interactions with tumor-associated macrophages and inflammatory signaling pathways." (PMID 42164471, 2026). "Overall, our findings point to a potential biological connection between inherited CD36 variation and bladder cancer-related pathways, underscoring the need for further validation in tumor tissues." (PMID 41745082, 2026). "This review summarizes the structure, ligands, functions, regulation, and clinical implications of CD36 in renal and bladder cancer." (PMID 42164471, 2026). "This study aimed to identify TIPE2 and CD36 expressions in cancer bladder and examine their relationship with clinicopathological data and prognosis." (PMID 40060230, 2025). "In MIBC-type bladder cancer, CD36 expression correlates to greater depth of tumor invasion (pT stage) and advanced stages of the disease (pT3b-T4)." (PMID 36568966, 2022). "Silencing of CD36 in human bladder cancer cells reduces the clonogenicity and the expression of stemness markers (ALDHA1, CD44, KLF4 and Nanog) induced by oxLDL exposure." (PMID 36568966, 2022). "Recent report show that CD36 elevated in exosomes derived from bladder cancer cells by proteomics analysis." (PMID 35069505, 2021). "CD36 is known to induce tumor progression and metastasis via altered lipid metabolism in various human cancers including bladder cancer." (PMID 34257543, 2021). "FATP4 revealed a mostly cytoplasmic and rare membranous staining in tumor cells, whereas CD36 was mainly expressed in the membrane and rarely in the cytoplasm of bladder cancer cells." (PMID 34257543, 2021). "In the current work, we analyzed IHC expression of CD36 in urinary bladder cancer tissue and found that immunopositivity of CD36 was significantly associated with high-grade, stages, greater lymph node invasion, high incidence of tumor recurrence, and higher rates of mortality." (PMID 40060230, 2025). "Indeed, CD36+ cells were previously highlighted as initiators of metastasis in mouse oral squamous cell carcinomas, and CD36 expression correlated drastically with poor prognosis in lung squamous cell cancer, bladder cancer, or luminal A breast cancer." (PMID 32029741, 2020). "Similarly, circZNF609 stabilizes the IGF2BP2/CD36 complex in bladder cancer to promote fatty acid uptake, thereby activating PPAR signaling and supporting lipid-dependent tumor growth while impairing T-cell metabolic fitness and reducing immunotherapy responsiveness." (PMID 41438756, 2025). "In bladder cancer, circZNF609 enhances fatty acid uptake via the IGF2BP2/CD36 pathway, leading to metabolic reprogramming that reduces tumor sensitivity to immunotherapy." (PMID 41438756, 2025). "Our study demonstrated a significant correlation between CD36 immunostaining and shorter both DFS and OS in patients with bladder carcinoma which means that CD36 overexpression was concomitant with tumors displaying highly aggressive behavior." (PMID 40060230, 2025). "For patients with hypercholesterolemic bladder cancer, serum ox-LDL can bind to CD36 and activate the JAK2-pSTAT3 pathway, thereby promoting the cancer stemness of bladder cancer, increasing cancer cell proliferation, and inducing epithelial-mesenchymal transition in vitro." (PMID 41281744, 2025). "Further validation and signaling pathway analyses revealed that ox-LDL binds to the bladder cancer cell membrane receptor CD36 and affects the intracellular JAK2-STAT3 signaling pathway, thereby regulating tumor cell stemness-related genes and promoting bladder cancer cell proliferation." (PMID 37653037, 2023).
bladder cancer (continued). "Although FATP4, CD36, and ACSL1 showed weak positive correlation among them in this study, it is uncertain if FATP4, CD36 or ACSL1 might interact with each other and have a synergistic effect on the transport of fatty acids in bladder cancer cells." (PMID 34257543, 2021). "Although CD36 and ACSL1 failed to predict OS and RFS in this NMIBC cohort, it could be assumed that CD36 and ACSL1 might have roles in the progression of bladder cancers and could be targetable along with FATP4." (PMID 34257543, 2021). "In addition, the expression levels of CD36 and CD44 in exosomes were identified via immunoblotting and flow cytometry, and results of this previous study revealed substantial differences in the expression of CD36 and CD44 between healthy individuals and patients with bladder cancer." (PMID 40612948, 2025). "High CD36 and ACSL1 failed to predict overall survival of bladder cancer patients." (PMID 34257543, 2021).
Hypercholesterolemia (17 papers, 2004 to 2025). An increased concentration of cholesterol in the blood. "Some increase in gene expression of CD36 and PPARg has occurred only in HUVECs incubated with lEVs isolated from hypercholesterolaemia patients." (PMID 39420340, 2024). "Animal and in vitro studies have suggested that hypercholesterolemia and increased oxidative stress predisposes to monocyte activation and enhanced accumulation of oxidized LDL cholesterol (oxLDL-C) through a CD36-dependent mechanism." (PMID 25875611, 2015). "The myeloid scavenger receptor CD36 binds oxidized lipoproteins that accumulate with hypercholesterolemia and mediates their clearance from the circulation and peripheral tissues." (PMID 15546489, 2004). "CD36 expression was increased in patients with hypercholesterolemia." (PMID 34307504, 2021). "Hypercholesterolemia may decrease NO production by promoting the interaction of caveolin and eNOS and by oxidized LDL/CD36-induced redistribution of eNOS from caveolae leading to the inability to efficiently activate eNOS." (PMID 23056485, 2012).
metastatic tumors (17 papers, 2016 to 2025). "Fatty acid uptake-related genes, such as caveolin-1 and CD36, are abundantly present in metastatic tumors and have been associated with EMT in multiple cancer." (PMID 32327627, 2020). "We analyzed the expression of CD36 in nine PDXs established from primary tumors and CRC metastasis, and found that CD36 (88kD) is mostly associated with PDX established from metastatic tumors with the exception of Pt 2568, which was established from primary CRC tumor." (PMID 32850342, 2020). "In this study, the cellular FA uptake genes CAV1 and CD36 were found to be amplified in metastatic tumors, their gene expression patterns were consistently associated with EMT scores across multiple cancer types and emerged as members of the predictive gene signature." (PMID 26725848, 2016). "Enhanced expression of the CD36 protein, which acts as both a signaling receptor and a fatty acid transporter (known as fatty acid translocase), has been recognized particularly in various metastatic tumors." (PMID 40723225, 2025). "Immunofluorescence staining of hepatic metastatic tumors showed that F4/80+/CD206+ double positive macrophage subpopulation was more abundant in WT mice than in Cd36−/− mice." (PMID 36184646, 2022). "Based on tissue analysis, we found that high expression of CD36 is primarily associated with CRC metastasis, suggesting that metastatic tumors are more dependent on FA uptake as compared to primary CRC." (PMID 32850342, 2020). "Our findings are supported by multiple studies showing the involvement of CD36 in metastatic disease." (PMID 32850342, 2020). "Moreover, metastatic tumors express more CD36 than primary tumors." (PMID 39062552, 2024). "Finally, as upregulation of CD36 correlates with poor prognosis and survival rate in patients with different cancers, and that its amplification correlates with metastasis in many human cancers, CD36 appears to be an interesting target for the management of metastatic disease." (PMID 31922096, 2019). "Furthermore, the appearance of CAV1 and CD36 across all the cancer types in this study clearly supports the role of elevated cellular FA uptake and accumulation in the progression and maintenance of metastatic tumors." (PMID 26725848, 2016). "CD36 is overexpressed in metastatic tumors, whereas the expression of CD36 is basically negative in primary tumors." (PMID 37978381, 2023). "Furthermore, an analysis of matched normal mucosa, primary CRC and CRC liver metastasis demonstrates and an increase in expression of CD36 and MMP28 and a decrease in the expression of E-cadherin as we move from normal tissues to primary and metastatic tumors." (PMID 35008415, 2022). "Genetic alterations in metabolic genes associated with metastatic progression analyzed, revealed that genes involved in cellular fatty acid uptake (CAV1, CD36) and de novo lipogenesis (PPARA, PPARD, MLXIPL) were specifically amplified at higher frequencies in metastatic tumors." (PMID 28798698, 2017). "However, 6 genes were amplified at significantly higher frequencies in metastatic tumors: SCO2 (p = 1.1 × 10−9), MLXIPL (p = 2.1 × 10−4), PPARA (p = 1.2 × 10−10), PPARD (p = 4 × 10−15), CAV1 (p = 3.4 × 10−4) and CD36 (p = 3.5 × 10−4)." (PMID 26725848, 2016). "However, genes involved in cellular FA uptake (CAV1, CD36) and de novo lipogenesis (PPARA, PPARD, MLXIPL) were specifically amplified at higher frequencies in metastatic tumors." (PMID 26725848, 2016).